SULF1 (sulfatase 1)
Diseases named in the same sentence as SULF1 in open-access papers (continued):
Sharing a sentence is not in itself a finding about the gene and the disease.
tumor (continued). "Although Sulf2 is purported to exhibit an oncogenic effect in HCC, in contrast, Sulf1 has been identified as having a tumor suppressor effect in HCC." (PMID 25105093, 2014). "Overall, it is conceivable to conclude that Sulf1 plays anti-tumor roles whereas Sulf2 plays tumor-promoting roles in several tumor types." (PMID 25105093, 2014). "Human Sulfatase 1 (HSulf-1), an endosulfatase established as a putative tumor suppressor in ovarian cancer, has been shown to modulate the signaling of growth factors and cytokines in tumor microenvironment." (PMID 25225614, 2014). "The tumor suppressor functions of SULF1 involve inhibition of co-receptor functions of cellular heparin sulfate proteoglycans (HSPGs)." (PMID 24690739, 2014). "Sulf-1 is largely reported as having a tumor suppressor activity, as described in HCC, myeloma, head and neck, breast, and pancreatic cancers." (PMID 24459635, 2014). "Heparanase, Sulf1, and Sulf2 drive a range of processes in the tumor microenvironment, many of which, in the case of heparanase and Sulf2 promote tumor malignancy, and some, in the case of Sulf1 inhibit malignancy." (PMID 25105093, 2014). "It has been shown that the two isoforms Sulf1 and Sulf2 seem to present different activities during tumor growth." (PMID 23984412, 2013). "Previously it was assumed that SULF1 has a tumor suppressor role, and it is downregulated in many tumor types." (PMID 23144729, 2012). "Despite similar substrate specificity, SULF1 has mainly tumor suppressor functions whereas SULF2 presents tumor promoting functions." (PMID 21599997, 2011). "A number of reports demonstrated that over-expression of Sulf-1 or Sulf-2 in tumor cell lines inhibited growth factor signaling in response to several factors, including FGF-2, HB-EGF, and HGF." (PMID 17460759, 2007). "To investigate whether SULF1+ CAFs influence tumor cell migration, we performed wound healing and migration assays using SCC35 cells (human squamous cell carcinoma cell line) exposed to different conditions." (PMID 41549062, 2026). "Notably, the inverse circularity measurements and structural evaluations using confocal microscopy support the notion that CAF‐derived Sulf‐1 modulates extracellular matrix remodeling, thereby creating a permissive niche for tumor progression." (PMID 41549062, 2026). "It has been reported that there is a significant correlation between SULF1 and BRCA risk, with high SULF1 expression in BRCA tissues, which may promote tumor growth and metastasis." (PMID 38590118, 2025). "Increased secretion of SULF1 may enhance the remodeling of the extracellular matrix in the tumor microenvironment, affecting the development of tumors and adjacent host cells." (PMID 38590118, 2025). "Furthermore, loss of SULF1 leads to decreased expression of the pro-apoptotic protein Bim via increased ERK signaling, promoting tumor cell survival and resistance to chemotherapy." (PMID 41373732, 2025). "Furthermore, both immunohistochemistry (IHC) and Western blotting identified elevated SULF1 expression and increased phosphorylation of SMAD2/3 (TGFB pathway activation) in tumor and peritumoral tissues from transgenic Sulf1-Tg mice compared with WT." (PMID 41373732, 2025). "Some studies have suggested that inhibiting SULF1 may target tumor cells by down‐regulating the RTK pathway." (PMID 38590118, 2025). "Mounting references showed the heparin-degrading endosulfatase SULF1 in cancers may contribute to affect cellular growth and survival signaling, tumor proliferation, migration, invasion, and angiogenesis in vitro and in vivo." (PMID 36622753, 2023). "Finally, our RNAScope study shows that SULF1+ cells localize to the stroma while SULF2+ cells overlap to a large degree with the cytokeratin+ tumor cells." (PMID 36428645, 2022). "Thus, our results agree with the reported upregulation of SULF-1 mRNA in this tumor although it isn’t known the role played by the enzyme in MPM development and progression." (PMID 36359323, 2022).
tumor (continued). "SULF1 is increasingly considered for its tumor suppressor effect." (PMID 35433683, 2022). "Besides the wide-scale overexpression in tumor tissues, SULF1 is significantly downregulated in KICH and THCA and SULF2 in PRAD but none of the studies reaches a 2-fold decrease." (PMID 36428645, 2022). "SULF1 is expressed in only 14% of tumor cells (n = 309 of 2215)." (PMID 36428645, 2022). "SULF1 is associated with poor survival in univariate analysis but, contrary to SULF2, loses a significant impact when analyzed in a multivariable model together with SULF2, age, gender, smoking history, tumor stage, and radiation therapy." (PMID 36428645, 2022). "The tumor suppressor effect of SULF1 was described under hypoxic conditions in solid tumors." (PMID 34107956, 2021). "Similarly, even though silencing of SULF1 has been mostly associated with poor prognosis in a variety of carcinomas, we hypothesize that these outcomes rely heavily on the signaling context, such as type of tumor, disease stage, spatial distribution of GAGases, specific ligands, and other factors." (PMID 32413029, 2020). "On the other hand, it has been found that the family of heparin-degrading endosulfatases involving SULF1 and SULF2 were implicated in the pathophysiology of numerous cancers, including HCC with an opposing action either as a tumor suppressor action with SULF1 or as an oncogenic action with SULF2." (PMID 33076548, 2020). "Sulf1 can act as a tumour suppressor, whereas Sulf2 activates pro-tumourigenic signalling pathways." (PMID 33037194, 2020). "Therefore, modification of the glycocalyx (HSPG in particular) in the tumor microenvironment by Sulf1, Sulf2, or heparanase affects cancer cell proliferation, signaling, invasion, and metastasis." (PMID 30135409, 2018). "Similarly to heparanase, the two extracellular endosulfatases, Sulf-1 and Sulf-2, were found to be dysregulated in a wide range of human malignancies where they affect the tumor microenvironment and cell signaling by modifying the structure and function of HS." (PMID 30413079, 2018). "However, the roles of Sulf1 and Sulf2 in different types of tumor growth under different microenvironments are ambiguous." (PMID 30135409, 2018). "Using data mining from published transcriptomic datasets of UBUCs (GSE31684 and GSE32894), SULF1 and SULF2 were identified as significant genes showing upregulation during tumor progression among those associated with the heparan sulfate proteoglycan metabolic process (GO:0030201)." (PMID 28525382, 2017). "Even though this finding suggested that sulfatase-1 could act as a tumor suppressor in HCC, caution should be exercised in interpreting it as no mesothelin expression was detected in human HCC specimen." (PMID 28218682, 2017). "In addition, nearly 40% of patients with high tumor SULF1 expression have the hepatoblast phenotype of HCC, which showed relatively poor survival." (PMID 28525382, 2017). "In cancer biology Sulf1 is thought to act as a tumour repressor but Sulf2 as a tumour enhancer." (PMID 27535874, 2017). "Furthermore, reduction in tumor growth and LNM were observed in Sulf-1-Hca-F group compared to the two control groups, which means that Sulf-1 played a role in the inhibition of tumor growth as well as reduction in lymphatic metastasis." (PMID 27626699, 2016). "This indicated that Sulf-1 played a tumor suppressor role in the hepatocarcinoma cells." (PMID 27626699, 2016). "However, such a generalisation appears to be misleading because there is evidence that in some instances Sulf-1 promotes, while Sulf-2 inhibits, tumour growth." (PMID 27408707, 2016). "It is of interest to note that as intimated in the PDAC setting, the tumor type, the Sulf isoform (Sulf1 and/or Sulf2), and the predominant pathway (Wnt or FGF2) might result in opposing effects of Sulf’s on tumor progression and metastasis." (PMID 25105093, 2014).
tumor (continued). "This section highlights some of the prevalent cancer types, which have reported significant alterations in heparanase, Sulf1, and/or Sulf2 and how these changes in expression correlate with indices of cancer progression such as prognostic indicators, tumor development, metastasis, and survival." (PMID 25105093, 2014). "However, in HCC tumor tissue, expression of Sulf1 is higher compared to adjacent benign tissues and approximately a third of HCCs express Sulf1 at high levels >1.5× the level in adjacent benign tissue." (PMID 25105093, 2014). "Similarly, SULF-1 has a dual role in enhancing or inhibiting various growth factor signaling pathways and by that tumor cell proliferation: as it has a tumor suppressor role in the majority of carcinomas." (PMID 24392351, 2013). "Over-expression of Sulf1 in tumor cell lines acts to inhibit FGF-dependent signaling." (PMID 17593974, 2007). "Thus, to desulfate HSPGs by SULF1 might have a tumor suppressor effect via abolishment of ligand-receptor binding and downstream signaling." (PMID 36622753, 2023). "Indeed, the role of SULF-1 in cancer appears to be more complex than initially thought and may correlate with the tumor type and stage." (PMID 36359323, 2022). "We can hypothesize that in our experimental settings SULF1 downregulation can contribute to inhibition of proliferation, given the fact that the level of SULF1 was found elevated in this tumor compared to the normal mesothelium and there are evidences that Wnt pathway is also altered." (PMID 23144729, 2012). "According to the subcutaneous tumor formation model results, the co-cul + shNC group displayed the biggest and heaviest tumor under CDDP treatments, while SULF1 knockdown inhibited the tumor growth." (PMID 38438372, 2024). "SULF1, an extracellular heparan sulfate endosulfatase, regulates key growth factor pathways such as FGF2 and VEGF, impacting angiogenesis and tumor progression." (PMID 39850570, 2024). "Sulf-1 is supplied to the tumors primarily by the CAF, while Sulf-2 is more abundant in the epithelial HNSCC tumor cells." (PMID 37958342, 2023). "To further strengthen the observation that SULF1 is expressed in fibroblasts and SULF2 in tumor cells, we analyzed the RNA-seq data from the Cancer Cell Line Encyclopedia (CCLE)." (PMID 36428645, 2022). "We have shown that SULF1 and SULF2 enzymes increase in tumor tissues of patients with HNSC and that the increase is associated with poor survival." (PMID 36428645, 2022). "The mean SULF1 mRNA, represented as log2(TPM+1), is 0.172 in tumor cells compared with 1.099 in fibroblasts (p < 0.001); the mean value of SULF2 mRNA is 1.145 in tumor cells compared with 0.386 in fibroblasts (p < 0.001)." (PMID 36428645, 2022). "An increase in extracellular sulfatase (SULF1 and SULF2) in human GBM regulates important interactions of growth factors and ECM components to PGs, thus mediating tumor cell invasion and proliferation." (PMID 35202840, 2022). "We conclude that SULF1 and SULF2 in HNSC derive primarily from the fibroblasts and tumor cells, respectively." (PMID 36428645, 2022). "The percentage of positive cells among individual patients ranges from 2.4–54.5% for SULF1 and 43.1–91.7% for SULF2 in tumor cells, and from 31.3–71.0% for SULF1 and 8.7–43.8% for SULF2 in fibroblasts." (PMID 36428645, 2022). "The largely podocyte-specific transcription factor Wilms’ tumor gene 1 (WT1) regulates the expression of SULF2 and SULF1, and children with this tumor exhibited a kidney phenotype similar to that in SULF2 and SULF1 knock-out mice." (PMID 33540508, 2021). "SULF1 and SULF2 act at the interface between tumor cells and their microenvironment, taking part in key interactions between local tumor and host cell interactions." (PMID 34249755, 2021). "The expression of SULF1 and SULF2 enzymes is differently regulated in a number of tumors, but their precise role in tumor growth has remained controversial." (PMID 34249755, 2021).
tumor (continued). "We observed that both SULF1 and SULF2 are significantly upregulated in HNSCC tumor with 5.1-fold and 2.2-fold increase compared to adjacent benign tissues, respectively (both p < 0.001, paired t-test)." (PMID 33585200, 2020). "We analyzed differential expression of both SULF1 and SULF2 in a group of 43 patients from the TCGA-HNSC with RNA-seq results of paired tumor and adjacent benign mucosal tissue." (PMID 33585200, 2020). "Both SULF1 and SULF2 expression in tumor samples showed significant differences among the four locations (p = 0.018 for SULF1, p < 0.001 for SULF2, one-way ANOVA)." (PMID 33585200, 2020). "The reaction is carried out by two endosulfatases located on the cell surface, SULF1 and SULF2, and alterations in the expression of these genes in various tumor types, either up- or downregulation, have been reported." (PMID 29940912, 2018). "In contrast, Sulf1 has been found to be downregulated in a number of cancer types while Sulf2 is typically overexpressed in carcinomas but importantly, these may be differentially expressed depending on the stage of cancer and the level of hypoxia in the tumor microenvironment." (PMID 25105093, 2014). "Inmunostaining and CISH techniques applied for SULF1 and SULF2 respectively corroborated this data, showing stronger staining in tumor cells relative to healthy ones." (PMID 23327652, 2013). "In this article, we focused on recent and challenging data describing the implication of SULF1 and SULF2 in human neoplasia." (PMID 21599997, 2011). "Proteomic analysis confirmed the absence of SULF1 in the knockout cell cultures and revealed that SULF2, expressed in tumor cells, does not compensate for its loss." (PMID 41549062, 2026). "In addition, the precise reasons for the different properties of SULF1 and SULF2, one a tumor suppressor in many biological contexts and the other an established oncogene, need to be determined." (PMID 40140347, 2025). "Also, we identified novel predicted tumor-suppressive ligands (SLIT3, DCN, CCN3, THBS1, INHA and INHBA), proteins (DNASE1L3, SULF1, PTEN, OAS1, and DAB2IP), and receptors (P2RX4, CDHR2, PTPRJ, and PTPRH) in MSC1 cells." (PMID 40564222, 2025). "SULF1 inhibits HSPG-mediated growth factor signaling, limiting tumor growth." (PMID 40564222, 2025). "The Sulf-1 protein is upregulated in the tumor tissues, but in general, is not detectable in cancer cell lines." (PMID 38825040, 2024). "The in situ hybridization clearly shows that SULF1-expressing cells are more common in the stroma (mean 24.9% stroma vs. 8.4% tumor, p < 0.001) while SULF2 expression is higher in the cancer cells (mean 22.7% stroma vs. 52.5% tumor, p < 0.001)." (PMID 36428645, 2022). "At the same time, we found two other tumor suppression genes, SETBP1 and SULF1." (PMID 35433683, 2022). "This suggests that SULF1 expression in fibroblasts of the tumor tissues is not unique for HNSC but is more likely a pan-cancer event." (PMID 36428645, 2022). "Neither PSAP nor SULF-1 expression showed a correlation with the tumor stage since the transcript levels were similar in all four stages." (PMID 36359323, 2022). "Whether F. nucleatum directly up-regulates SULF1 and/or MMP2 through epigenetic mechanisms or ECM remodeling by gene degradation plays a role in initial HNSCC tumor growth remains an interesting question warranting further investigations." (PMID 33218162, 2020). "The fold-change of SULF1 and SULF2 upregulation in tumor among these 43 patients are moderately correlated (Pearson’s r = 0.563, p < 0.001), as is the mRNA expression in tumor tissues in all 499 patients (r = 0.390, p < 0.001)." (PMID 33585200, 2020). "As examples, the only significant gene in the epithelial compartment, ALCAM was overexpressed in the epithelial component of Gleason 8 tumors, and the stromal gene SULF1 was highly expressed in stroma adjacent to high-grade, but not low-grade tumor." (PMID 28871082, 2017).
tumor (continued). "However, in HCC, miR-21-mediated inhibition of SULF1 and PTEN promoted growth factor signaling and tumor progression." (PMID 28672878, 2017). "SULF1 may be a new target in searching drug treatment of HCC and may be a potential biomarker for the progression of tumor." (PMID 28819584, 2017). "Heparanase, Sulf1, and Sulf2 have been shown, by virtue of their enzymatic modification of the ECM, to affect the signaling of a number of proteins that are important drivers of tumor growth or progression." (PMID 25105093, 2014). "Rather than having uniformly tumor-promoting properties, Sulf1 and Sulf2 have pro- and anti-tumor affects." (PMID 25105093, 2014). "Another mechanism, recently discovered, by which heparanase is able to promote tumor malignancy is via the stimulation of exosome secretion, although as yet Sulf1 and Sulf2 have not been shown to be involved in this process." (PMID 25105093, 2014). "However, if heparanase is clearly associated to protumorigenic effects, contradictory observations have been made concerning SULF1 and SULF2 contribution in human neoplasia, as we have discussed in this article." (PMID 21599997, 2011). "In the head and neck squamous carcinoma, SULF1 acted as a negative factor in tumor cell growth." (PMID 38438372, 2024). "Given that CAFs are reported to be an important stromal component and are critically involved in tumor progression, we reclustered the CAFs and further categorized them into two main types: inflammatory CAFs (iCAFs; CFD, CKB, and DPT) and myoblastic CAFs (myCAFs; INHBA, SULF1, and COL8A1)." (PMID 36725337, 2023). "In carcinomas, SULF-1 and SULF-2 are usually downregulated and overexpressed, respectively, but their expression may change depending on tumor stage and the hypoxia level in the tumor microenvironment (TME)." (PMID 36359323, 2022). "In our study, RT-qPCR data showed down-regulation of SULF1 expression levels in CRC tissues compared to the adjacent normal tissues, although its expression levels showed significantly increased levels in patients with more advanced stage and metastasis of the tumor." (PMID 34107956, 2021). "Although both Sulf isotypes show similar substrate specificity, conflicting studies, in particular for Sulf1, suggest that the functional consequences of HSPG modification may depend on experimental conditions (in vitro vs. in vivo), context and tumour or tumour subtype." (PMID 33037194, 2020). "Interestingly, the mean expression of SULF1 in SULF1-positive cells remains significantly higher in fibroblasts than in tumor cells (2.291 vs. 1.232, p < 0.001); however, the mean expression of SULF2 in SULF2-positive fibroblasts and tumor cells is the same (1.826 vs. 1.812, p = 0.8)." (PMID 36428645, 2022). "This indicates that the Sulf‐2 in the cocultures did not compensate for the lack of Sulf‐1, which further supports the importance of Sulf‐1 provided by CAF in the tumor microenvironment." (PMID 41549062, 2026). "Even though they exhibited consistent tumor-normal dysregulation, five genes (COL12A1, CTSB, PLOD1, SPP1, and SULF1) were excluded from the final candidate list as they did not satisfy the meta-analysis criteria and exhibited loss of prognostic significance." (PMID 41451347, 2025). "However, SULF1 and SULF2 mRNAs are >20-fold higher in the PDAC tumor tissues than in the non-disease pancreatic tissue from the GTEx (SULF1 log2FC = 6.81, SULF2 log2FC = 4.85, both p < 0.001), which is consistent with the large difference in the protein expression." (PMID 36428645, 2022).